RHOA (ras homolog family member A)
Diseases named in the same sentence as RHOA in open-access papers (continued):
Sharing a sentence is not in itself a finding about the gene and the disease.
tumor (continued). "Furthermore, a study of K-Ras-driven liver tumorigenesis in Zebrafish has found that an active form of RhoA (RhoAG14V) hindered tumor formation whereas dominant-negative RhoA (RhoAT19N) accelerated tumorigenesis." (PMID 26030593, 2015). "Several previous studies of the relationship between RhoA and Ras signaling in cell transformation prompted our current investigation of whether RhoA or RhoC are required for K-Ras-induced tumor formation." (PMID 26030593, 2015). "Although RhoA/ROCK pathway has been shown to be implicated in DPT-induced suppression of tumor vasculature, the molecular mechanisms involved have not been fully characterized." (PMID 26470595, 2015). "Our investigation of these genetic studies produced surprising results that individually RhoA and RhoC are dispensable for the oncogenic K-Ras induced lung tumorigenesis and loss of RhoA alone exacerbates, rather than suppresses, tumor initiating activity." (PMID 26030593, 2015). "In addition, using the viability response phenotype of C36L1, we observed that downregulation of RhoA and consequently of PTEN in tumor cells resulted in loss of C36L1 properties at low concentrations." (PMID 26391685, 2015). "In this case, RhoA signaling would be required for tumor maintenance." (PMID 26030593, 2015). "Notably, similar to the knockdown of RhoA, c-Myc knockdown diminished RhoA expression as well as filamentary F-actin in tumor cells induced by PIWIL2." (PMID 25193865, 2014). "In ErbB-2-overexpressing tumours, ErbB-2 signals through Plexin-B1 and RhoA to promote metastasis." (PMID 25137062, 2014). "Whether RhoA/ROCK is involved in regulating the formation of tumor cell vasculogenic mimicry (VM) is largely unknown." (PMID 25238232, 2014). "Rac and Cdc42 counteract RhoA signalling pathways and promote tumour cell invasion." (PMID 24810913, 2014). "Given our finding that the mutated RHOA allele frequencies distributed below 0.05 in many AITL samples, the tumor cell content might be very low and could be detected in some cases only when the cut-off levels of qAS-PCR and deep sequencing are lowered." (PMID 25310466, 2014). "More active RhoA in tumors with lymph node involvement than in those that did not metastasize suggests increased RhoA function is associated with enhanced tumor cell motility." (PMID 24646293, 2014). "The effects of thapsigargin on cell death in A549 tumor cells may be mediated by mTORC1-RhoA-Cofilin-1 pathway, because thapsigargin treatment may dramatically inhibit mTORC1 activity and RhoA protein level." (PMID 24605059, 2014). "Therefore, it is likely that RhoA and RhoC represent a subset of proteins important for tumor cell invasion that are affected by PFIs and that protein prenylation in general remains the primary target of PFIs." (PMID 24587105, 2014). "The overexpression of RhoA/ROCK has been reported in many tumor types, including glioma." (PMID 24642531, 2014). "Interestingly, G12 subfamily can couple to the CXCR4 chemokine receptor and drive tumor spread to specific organs in RhoA dependent manner." (PMID 25275299, 2014). "In addition, a high expression of RhoA induces metastatic properties and increases tumor invasiveness." (PMID 24642531, 2014). "By contrast to RhoA and RhoC reported to be up-regulated in several types of cancers, RhoB displays a property that may participate in tumor suppression." (PMID 24223801, 2013). "Indeed, increased RhoA expression was described in various human tumours to correlate with poor prognosis." (PMID 23388133, 2013). "Recently, RhoA has been found to function in vesicle trafficking, tumor invasion and metastasis." (PMID 23538840, 2013). "However, other in vitro studies of TGF-β-induced EMT have identified miR-155, by RhoA targeting, and especially the miR-200 family in tumor metastasis, by targeting E-cadherin transcriptional repressors ZEB1/ZEB2, as EMT-promoting miRNAs." (PMID 23441172, 2013).
tumor (continued). "RhoA can reorganize the cell cytoskeleton and regulate cell migration by activating effector proteins such as Rho-associated coiled-coil kinase (ROCK); such changes are associated with tumor invasion and migration in several types of carcinoma cells." (PMID 24351810, 2013). "The results of this study provide conclusive evidence that loss of DLC1, combined with an oncogenic stimulus, promotes HCC in vivo and that this oncogenic process is associated with activation of RhoA, which is a key consequence of loss of DLC1 tumor suppressor activity." (PMID 22580498, 2012). "Little is known about the RhoA GEFs that stimulate actinomyosin contractility during migration; however, identification of specific RhoA GEFs that drive tumor cell invasion would be important to design new therapeutic strategies to prevent tumor cell spreading and metastasis." (PMID 23185572, 2012). "On the other hand, TGF-β can rapidly activate the Rho-family GTPases, Rac1, CDC42, and RhoA, in normal and tumor cells, although the mechanism is still unknown." (PMID 22614218, 2012). "Finally, the mTOR inhibitor Rapamycin enhanced the effect of GSI on RhoA expression, resulting in down regulation of phospho-Akt and increased in vitro tumor cytotoxity." (PMID 22074495, 2011). "More specifically, constitutive active Raf-1 and RhoA cooperate in order to transform rat intestinal epithelial cells, providing them with a spindle-like morphology, anchorage independent growth and capacity to form tumours in athymic nude mice." (PMID 21943101, 2011). "The tumor weight and the tumor volume were significantly declined in Ad-RhoA-RhoC group." (PMID 20828398, 2010). "TUNEL assay also showed higher death of tumor xenograft tissue cells in Ad-RhoA-RhoC group." (PMID 20828398, 2010). "In addition, the mean tumor weight in NS, Ad-HK and Ad-RhoA-RhoC group was (0.75 ± 0.22) g, (0.78 ± 0.22) g and (0.36 ± 0.13) g, respectively." (PMID 20828398, 2010). "Furthermore, Faried A. and colleagues identified that RhoA promoted tumour growth more than RhoC, while RhoC induced distant metastasis in comparison to RhoA." (PMID 19374769, 2009). "The effects of altered NET1 and RhoA levels on tumour cell chemotaxis were examined in vitro." (PMID 18827818, 2008). "Rac1 and RhoA were antagonistic regulators of both basal and stimulated tumour cell NHE1 activity." (PMID 15535843, 2004). "Importantly, these results also unify recent advances concerning the mechanisms underlying tumour invasive potential: the RhoA-ROCK activation of NHE1, the RhoA-ROCK mediation of invasion and role of the NHE1 in driving tumour cell motility and invasion." (PMID 15535843, 2004). "Accordingly, the questions are whether RhoA and Rac1 reciprocally regulate motility in tumour cells of epithelial origin, and if so then do they act via a coordinated regulation of NHE1 activity?" (PMID 15535843, 2004). "We observed that serum deprivation inhibits RhoA activity and stimulates Rac1 activity and, using dominant negative and constitutively active mutants, that Rac1 and RhoA are antagonistic regulators of tumour cell NHE1 activity." (PMID 15535843, 2004). "However, contradictory reports exist, where RHOA has been shown as tumor suppressive." (PMID 40600795, 2025). "However, accumulating clinical evidence reveals that wild-type RHOA (WT-RHOA) is frequently hyperactivated in human cancers, with particularly elevated activity observed at invasive tumor fronts and metastatic sites, suggesting alternative activation mechanisms beyond genetic mutations." (PMID 41291745, 2025). "Furthermore, the expression of Ki67 in YTsh–GNAQ mouse tissues was greater than that in YTOE–vector mouse tissues, and Ki67 expression was lower in the tumour tissues of mice overexpressing RHOA, indicating that RHOA overexpression inhibited tumour cell proliferation." (PMID 41362935, 2025).
tumor (continued). "Moreover, the EphA2/focal adhesion kinase (FAK)/RhoA signaling pathway has been reported to play an important role in the malignant behavior (i.e., resistance to apoptosis, cell migration, invasion, and angiogenesis) of tumor cells." (PMID 41440001, 2025). "Therefore, to quantify activated RhoA in the tumor lysates, we used the RhoA-GTP antibody to pull down activated RhoA from the samples, which we could then visualize and quantify with a RhoA antibody." (PMID 41338458, 2025). "Notably, RhoA regulates immune cell differentiation and function, recruits innate immune cells (including neutrophils and macrophages), enhances the antigen presentation ability of immune cells, forms immune synapses, and improves the tumor microenvironment." (PMID 38528546, 2024). "Therefore, PRUNE2 prevents oncogenic transformation of prostate cells and may control tumor growth through RhoA downregulation." (PMID 38896642, 2024). "Moreover, mTORC1 can stimulate RhoA signaling in cancer cells, which can foster tumor metastasis." (PMID 39406918, 2024). "Interestingly, sites of active MV release serve as convergence points of multiple intracellular trafficking pathways, of which many components are subsequently loaded in tumor MVs, such as the Ras-related GTPases RhoA, Rab22a, and Rab35, and the ADP-ribosylation factor 6 (ARF6)." (PMID 37760395, 2023). "Previous studies have demonstrated that emodin could inhibit RhoA and Rock1 on gene and protein levels, and it can also suppress the phosphatidylinositol 3-kinase-Cdc42/Rac1 pathway, resulting in the restrained migratory movement of tumor cells." (PMID 36969843, 2023). "Moreover, the CXCR4/RhoA pathway is involved in tumor progression in digestive tract tumors." (PMID 35941537, 2022). "In addition, we revealed a novel role of eIF3a in tumor acquisition of invasive properties, including abundant pseudopodia formation and cytoskeleton reconstruction, by translationally regulating the expression of Cdc42 and RhoA." (PMID 35300416, 2022). "Contrary to recent studies that report the identification of new driver mutations in some RHO GTPases members, such as RAC1, RHOA, and CDC42, analysis of cancer genomes has demonstrated that mutations affecting RHO signaling pathways are found at low frequency in a limited spectrum of tumor types." (PMID 34771549, 2021). "Moreover, RhoA and Rac1/Cdc42 activities, coordinated in regulating both membrane protrusions and cell matrix adhesions, have opposing effects on different modes of tumor cell motility." (PMID 33477952, 2021). "It remains unclear whether RhoA plays a cell-intrinsic role in regulatory T (Treg) cells that suppress effector T cells such as Th2/Th17 cells to maintain immune tolerance and to promote tumor immune evasion." (PMID 34721389, 2021). "Activation of RhoA can led to increased intracellular oxidative stress; regulated intercellular adhesion mediated by cadherins; increased the expression of fibrogenic growth factors, extracellular matrix components and inflammatory cytokines; and changed tumor cells' invasion and migration." (PMID 34345201, 2021). "Thus, we can summarize that RhoA activity up-regulated could suppress tumor effectively which is largely consistent with prior studies." (PMID 34285193, 2021). "Furthermore, p190Rho-GAP has been shown to be activated and reduce RhoA-activity in a Rac1-dependent manner in tumor cells and fibroblasts and RA-Rho-GAP and ARAP3 are activated by binding of Rap1, probably inducing the downregulation of RhoA in smooth muscle cells." (PMID 33906663, 2021). "In support of this assertion, tumour cells injected into mice models and treated with blebbistatin, an inhibitor of the RhoA downstream effector myosin II, exhibited reduced intravascular survival and subsequently arrest, which could explain the delay on metastatic onset that was observed." (PMID 34241735, 2021).
tumor (continued). "However, whether the RhoA/SF axis regulates tumor growth and metastasis through organizing periFN assembly remains uninvestigated." (PMID 33158289, 2020). "Interestingly, higher Pin1 and RhoC expression were significantly associated with smaller tumor, and high RhoA also demonstrated such trend, which might be due to dissemination of HCC cells from the primary tumor." (PMID 31324164, 2019). "However, recent whole-genome sequencing studies of cancers raised the possibility that RhoA may have a tumor suppression function." (PMID 31705019, 2019). "Furthermore, unlike mock/WT, the RHOA-mutated tumor cells had little antitumor host reaction in the invasive front, which is similar to the pattern of mucosal invasion in clinical RHOA-mutated DGC." (PMID 31485674, 2019). "Thus, to examine whether CLOCK and BMAL1 can promote tumor cell proliferation via RHOA, the Cell Counting Kit-8 assays were introduced to observe cell proliferation in HeLa cells." (PMID 30287810, 2018). "In addition, F-actin, regulated by RHOA, has been shown to participate in tumor progression." (PMID 30287810, 2018). "In addition, the increase of RhoA activity reduced the expression of ZO-1 and disrupted the tight junction between the endothelium, which eventually led to the increase of vascular endothelial permeability and promotes tumor metastasis." (PMID 30064461, 2018). "Thus, RhoA may act as a tumour suppressor not only by restricting tumour cell motility but also by inducing anoikis." (PMID 30166526, 2018). "Interestingly, activated RhoA-Rho kinase is strongly implicated in the damaging effects of CA4P on HUVEC and we recently reported that in vivo administration of a Rho kinase inhibitor partially protected tumour blood vessels against CA4P-induced shut-down." (PMID 29221156, 2017). "Interestingly, platelets strongly increased RhoA activation in these tumor cells." (PMID 28827520, 2017). "Importantly, in various tumor cells, RhoA and Rac1 expression and/or activity is increased." (PMID 28419128, 2017). "Given that treatment with the ROCK inhibitor Y-27632 prevents anoikis, tumor cells harboring the ROCK1 nonsense mutation might be resistant to anoikis through the impairment of the Rho-ROCK pathway, similar to tumor cells harboring the RHOA L57V mutation." (PMID 26811494, 2016). "In addition, RhoA expression correlates to tumour grade in astrocytomas." (PMID 26132659, 2015). "Another caution interpreting our results is that both mouse cancer models are accompanied by significant inflammatory responses which could potentially be modulated by RhoA status, which in turn may be promoting the inflammatory component (i.e. effects through tumor microenvironment)." (PMID 26030593, 2015). "Moreover, RhoA can also promote tumor cell invasion through regulating invadopodia formation." (PMID 23538840, 2013). "These two modes of movement are inter-convertible and tumour cells may undergo amoeboid-mesenchymal and mesenchymal-amoeboid transitions that seem to be controlled by an antagonism between the Rac1 and RhoA signalling pathways." (PMID 23144867, 2012). "And further research work should be done to examine the downstream effectors of RhoA and RhoC; such as ROCK-I and ROCK-II, being most associated with metastasis and progress in cancer, which will be benefit for exploring the possible molecular mechanisms of RhoA and RhoC in tumor inhibition." (PMID 20828398, 2010). "Then we further identified that ANLN-mediated Hippo signaling suppression is dependent on active RhoA-GTP, which is also crucial for ANLN-mediated promoting-tumor in ICC." (PMID 41513610, 2026). "Here, our findings identified the ANLN/RhoA/YAP1/TEAD1 positive feedback axis in ICC, which was essential for cytokinesis and tumor growth." (PMID 41513610, 2026).
tumor (continued). "In this study, we demonstrated that ANLN contributed to ICC growth via the RhoA/LATS1/YAP1 axis, establishing a link between ANLN and the Hippo pathway, which broadened the understanding of the role of ANLN in tumor." (PMID 41513610, 2026). "These CAFs activate signaling pathways including RhoA/ROCK, JAK/STAT3, and MAPK, fostering tumor progression." (PMID 41583435, 2025). "In previous studies, we observed that samples from active MM patients exhibit activation of the PI3K/AKT and RhoA/ROCK1 signaling pathways, which are known to facilitate tumor cell proliferation." (PMID 39953613, 2025). "Recent studies have shown that ECT2 can abnormally activate RhoA, and then the activated RhoA binds to ROCK, participating in the abnormal proliferation and migration of various tumor cells by mediating various cascade reactions." (PMID 40655948, 2025). "In liver cancer, ANLN promotes PLK1-mediated phosphorylation of RACGAP1 and subsequent activation of RhoA, thereby ensuring mitotic accuracy, whereas ANLN inhibition disrupts mitosis and effectively suppresses tumor growth." (PMID 41573677, 2025). "Unlike that study, we directly silenced EphA2 using shRNA in a syngeneic, immunocompetent orthotopic model, providing in vivo mechanistic evidence that EphA2 depletion attenuates tumor growth and apoptosis resistance while suppressing the EphA2/FAK/RhoA axis." (PMID 41440001, 2025). "Numerous studies have demonstrated that RhoA/ROCK signaling is involved in actin polymerization and accelerates F-actin rearrangement, which enables tumor cells to traverse the ECM, thereby increasing the invasive capacity of BC cells." (PMID 40388100, 2025). "In cancer cells, ANLN participates in multiple signaling pathways, including activation of the RhoA/ROCK/myosin II axis, to enhance tumor cell migration." (PMID 41573677, 2025). "While this study focuses on the cell–intrinsic functions of the GNAQ/RHOA axis in NKTCL cells, the impact of RHOA signalling within the tumour microenvironment (TME) remains to be elucidated." (PMID 41362935, 2025). "Fifty‐one candidate proteins were identified, and we selected three top‐ranked, tumor‐related candidates (STK33, CLCN3, and RhoA) from the top 15 ranked proteins for further validation using SPR assays." (PMID 40908551, 2025). "GTPBP4 is a GTPase that plays a crucial role in 60S ribosome biogenesis and is responsible for tumor metastasis in CRC by disrupting the actin cytoskeleton, which is mediated by the reduced RhoA activity." (PMID 39949372, 2025). "The RhoA/ROCK pathway is critical for cytoskeletal remodelling, cell motility, and contraction, which are essential for tumour cells to form tube-like structures in VM." (PMID 41294859, 2025). "In anaplastic thyroid carcinoma, ANLN interacts with RhoA to activate the PI3K/AKT pathway and facilitate tumor progression." (PMID 41573677, 2025). "The impact of Sema4D on VM was mediated through the RhoA/ROCK pathway, which governs tumor cell plasticity and migration." (PMID 38375479, 2024). "Western blots confirmed downregulation of SRC/YAP1 and SRC/RHOA signaling axis in the DAB2 downregulation cells, and validated tumor growth inhibition of DAB2." (PMID 38481347, 2024). "A few studies have reported that hypusinated eIF5A promotes translation of RhoA and MYC in tumor cells." (PMID 38654332, 2024). "The tumor driver CTNND1 is the key component involved in cell–cell adhesion and Rac1, Cdc42, and Ras homolog gene family member A (RhoA) activation and has been reported to repress the migration and invasion of tumor cells." (PMID 39338204, 2024). "METTL14, through the modulation of TGFβ via the RhoA and PI3K-AKT pathways, contributes to tumor angiogenesis and progression." (PMID 38408075, 2024). "We therefore assessed the response of 451Lu-tumour bearing NSG mice on the opposite targeting of p110δ PI3K and RhoA." (PMID 38182748, 2024).